TFCP2 (transcription factor CP2)
Diseases named in the same sentence as TFCP2 in open-access papers (continued):
Sharing a sentence is not in itself a finding about the gene and the disease.
synovial sarcoma (4 papers, 2022 to 2025). "A subset of mesenchymal neoplasia is definitionally cytokeratin‐positive, including epithelioid sarcoma, synovial sarcoma, and the recently recognized TFCP2‐rearranged spindled and epithelioid rhabdomyosarcoma." (PMID 40640075, 2025).
colon cancer (3 papers, 2017 to 2026). "In conclusion, the expression of CD55 in colon cancer was associated with the genetic regulation of TFCP2, NF-κB, epigenetic regulation of miR-27a-3p, and methylation modification." (PMID 36741376, 2022). "Our results indicated that CD55 is regulated by TFCP2, NF-κB, miR-27a-3p, and several immune-related genes, which in turn affects colon cancer." (PMID 36741376, 2022). "In a study on the colon cancer, researchers found that KRAS mutations can activate the transcription factor TFCP2, which in turn upregulates the expression of adipogenic factors BMP4 and WNT5B, ultimately inducing CAFs to transform into a special subtype rich in lipids." (PMID 41469334, 2026). "In addition, both TFCP2 mRNA and protein were up-regulated in colon cancer, and high TFCP2 expression correlated with large tumor size, advanced pN stage, advanced AJCC stage, high Ki-67 index and worse prognosis." (PMID 29050300, 2017). "Previous studies have reported that the expression of TFCP2 was elevated in HCC and colon cancer." (PMID 29050300, 2017).
depression (2 papers, 2018 to 2025). "EMILIN3, OPA3, and TFCP2 are likely to be potential shared hub genes in both COVID-19 and depression." (PMID 40918512, 2025). "Furthermore, in the GSE101521 dataset, OPA3 and TFCP2 genes, but not EMILIN3, were found in the HP–depression enrichment pathway." (PMID 40918512, 2025).
epilepsy (2 papers, 2017 to 2018). A brain disorder characterized by episodes of abnormally increased neuronal discharge resulting in transient episodes of sensory or motor neurological dysfunction, or psychic dysfunction. "TFCP2 binds the acid-sensing ion channel 2a (ASIC2a) gene’s core promoter segment and thereby regulates ASIC2a expression that affects susceptibility to epilepsy." (PMID 30241344, 2018). "We report that suppressed TFCP2 expression and elevated ASIC2a expression were associated with glucose hypometabolism in the hippocampi of humans with epilepsy and of rat epilepsy model brains." (PMID 28725010, 2017). "Our data showed that hippocampal TFCP2 expression was suppressed in patients with epilepsy exhibiting glucose hypometabolism, in epileptic rats, and in glucose-deficient PC12 cells." (PMID 28725010, 2017). "Interestingly, nuclear TFCP2 expression was greatly reduced in the acute phase of epilepsy." (PMID 28725010, 2017).
lung adenocarcinoma (2 papers, 2021 to 2022). A carcinoma that arises from the lung and is characterized by the presence of malignant glandular epithelial cells. "In lung adenocarcinoma, YAP diminished intracellular iron levels by promoting FTL transcription through transcription factor CP2 (TRCP2)." (PMID 35979359, 2022).
mesenchymal chondrosarcoma (2 papers, 2022 to 2025). A morphologic variant of chondrosarcoma arising from bone and soft tissue. "Due to the epithelioid morphology and positivity for CK, the differential diagnosis of TFCP2-RMS is broad and includes, amongst others, metastatic carcinoma, alveolar RMS and mesenchymal chondrosarcoma." (PMID 35875137, 2022).
mesenchymal tumor (2 papers, 2024). "TFCP2-rearranged RMS (TFCP2-RMS) is a spindle cell/sclerosing and very aggressive mesenchymal tumor with rhabdomyoblastic differentiation, characterized by EWSR1/FUS::TFCP2 rearrangements." (PMID 38491228, 2024). "TFCP2-rearranged RMS (TFCP2-RMS) are spindle cell/sclerosing and very aggressive mesenchymal tumors with rhabdomyoblastic differentiation and EWSR1/FUS::TFCP2 rearrangements." (PMID 38217715, 2024).
temporal lobe epilepsy (2 papers, 2017 to 2018). A localization-related (focal) form of epilepsy characterized by recurrent seizures that arise from foci within the temporal lobe, most commonly from its mesial aspect. "Our findings suggest that hippocampal glucose hypometabolism elevates ASIC2a expression by suppressing TFCP2 expression, which further enhances the intrinsic excitability of CA1 pyramidal neurons and increases seizure susceptibility in patients with temporal lobe epilepsy." (PMID 28725010, 2017).
COVID-19 (1 paper, 2025). A disease caused by infection with severe acute respiratory syndrome coronavirus 2. "We used LASSO and RF methods to identify EMILIN3, OPA3, and TFCP2, as potential hub genes for both COVID-19 and MDD." (PMID 40918512, 2025). "Conversely, TFCP2 expression levels were notably down-regulated in both the COVID-19 and MDD datasets." (PMID 40918512, 2025). "Furthermore, OPA3 and TFCP2 are found in the DEGs expressed in peripheral blood neutrophils of COVID-19 patients." (PMID 40918512, 2025). "Furthermore, when comparing COVID-19- and MDD-related hub genes, we found that three genes, i.e., TFCP2, OPA3, and EMILIN3, overlapped." (PMID 40918512, 2025).
metastatic tumors (1 paper, 2017). "The functional study showed that forced expression of TFCP2 in less aggressive HCC cells resulted in highly aggressive, angiogenic and multi-organ metastatic tumors in nude mice." (PMID 29050300, 2017).
Parkinson disease (1 paper, 2018). A progressive degenerative disorder of the central nervous system characterized by loss of dopamine producing neurons in the substantia nigra and the presence of Lewy bodies in the substantia nigra and locus coeruleus. "TFCP2 is also associated with progressive supranuclear palsy (PSP), the second most common form of parkinsonism after Parkinson’s disease." (PMID 30241344, 2018).
sarcomatoid carcinoma (1 paper, 2025). A malignant epithelial neoplasm characterized by the presence of spindle cells and anaplastic morphologic features. "TFCP2-mutated tumors express an epithelioid component and show strong and diffuse CK positivity, which may prompt an erroneous diagnosis of sarcomatoid carcinoma, specifically in head and neck tumors with mucosal involvement." (PMID 41497928, 2025).
skin cutaneous melanoma (1 paper, 2023). "Interestingly, high TFCP2 expression (p = 0.049) and low SULF1 expression (p = 0.039) significantly correlated with poorer overall survival outcomes for patients with skin cutaneous melanoma." (PMID 37061003, 2023).
spindle cell tumors (1 paper, 2023). "ES-RMS with TFCP2 rearrangement is a rare malignant tumor and easily confused with other epithelioid or spindle cell tumors, it may harbor additional gene alteration in addition to TFCP2 rearrangement, such as MET mutation, increased copy numbers of EWSR1 and ROS1 gene, high TMB." (PMID 36998041, 2023).
cancer (24 papers, 2015 to 2025). A tumor composed of atypical neoplastic, often pleomorphic cells that invade other tissues. "While TFCP2 remains an interesting target for cancer, the underlying molecular mechanisms of its role in tumorigenesis are uncertain." (PMID 37061003, 2023). "They found that TFCP2-ChIP targets in SK-HEP-1 were functionally associated with cancer, cell movement, cell cycle, cell-to-cell signaling and interaction, cellular growth and proliferation." (PMID 30704465, 2019). "Pathways 6, and 8 based on ChIP on chip in TFCP2-HA-SK-HEP-1 were associated with cancer, and pathways 2, 6, and 8 in HepG2 cells were associated with cell adhesion and motility related pathways." (PMID 25609232, 2015). "LSF (encoded by TFCP2) is an evolutionarily conserved transcription factor that is normally expressed ubiquitously at low levels, but is significantly overexpressed in multiple specific cancers." (PMID 32539694, 2020). "The only known genetic alterations affecting TFCP2 in cancer are the recently discovered fusions to FUS and EWSR1 in atypical RMS." (PMID 38168093, 2024). "In the current study, we investigated a top hit from recent CRISPR/Cas9 screens, the alpha-globin transcription factor TFCP2, to investigate its role in regulating HS assembly in human cancer cells." (PMID 37061003, 2023). "Historically, TFCP2 has been studied primarily in the context of development and as a pro-oncogene in human cancers, yet little is known about its role in controlling glycosylation." (PMID 37061003, 2023). "Factor quinolinone inhibitors (FQIs), a first-in-class set of small molecule inhibitors targeted to the transcription factor LSF (TFCP2), exhibit promising cancer chemotherapeutic properties." (PMID 35704642, 2022). "In previous studies, TFCP2 was mostly considered a transcription factor that promotes the development and metastasis of cancer." (PMID 35193647, 2022). "The sequestration of miR-136 by hsa_circ_0023404 further promotes the yes-associated protein 1 (YAP) signaling pathway via transcription factor CP2 (TFCP2) and cancer progression, resulting in an impaired prognosis." (PMID 34830902, 2021). "The downregulation of RFX1 has been shown to predict poor prognosis in patients with small hepatocellular carcinoma, while TFCP2/TFCP2L1/UBP1 has been found to act as a TF in cancer." (PMID 32391054, 2020). "In cancer cells, the balance was disrupted due to the up-regulation of TFCP2, which led to the activation of beta-catenin/TCF signaling." (PMID 29050300, 2017). "As regard TFCP2-ChIP targets in SK-HEP-1, the functions associated with cancer, cell movement, cell cycle, cell-to-cell signaling and interaction, cellular growth and proliferation were also significantly enriched." (PMID 25609232, 2015). "Transcriptome analysis showed that alteration of TFCP2 in HCC cells led to change of genes in biological functions involved in cancer, cellular growth and proliferation, angiogenesis, cell movement and attachment." (PMID 25609232, 2015). "For example, TFCP2 has been described as a pro-oncogenic factor in breast cancer, pancreatic cancer, and hepatocellular carcinoma, although it can also act as a tumor suppressor in other cancers such as melanoma." (PMID 40813991, 2025). "Furthermore, the association of TFCP2 and UBP1 with several cancer types, coupled with the parallels between certain mechanisms of placental development and tumor growth, have led to the recent study of TFCP2L1 as a prognostic marker for cancer." (PMID 40813991, 2025). "Intriguingly, we found that knockdown of TFCP2 in human cancer cell lines from other tissues (lung, breast, liver, and cervix) did not give a similar phenotype, suggesting that TFCP2 may regulate HS assembly in a tissue- or cell-specific manner." (PMID 37061003, 2023). "The TF, TFCP2, plays a crucial role in cancer incidence and development." (PMID 33892791, 2021).
cancer (continued). "For example, there are numerous parallels between placental development and cancer growth; therefore, investigating the roles of TFCP2, TFCP2L1, and UBP1 in the placenta may help us better understand their functioning in cancer, as is evidenced by the studies of various other proteins and pathways." (PMID 30241344, 2018). "A striking example is the recent work on TFCP2-rearranged RMS, a highly uncommon cancer type whose characterization was driven by observations from routine clinical care." (PMID 40427586, 2025). "TFCP2 is known to be important in reproduction, cell cycle, hematopoiesis, expression of Human Immunodeficiency Virus (HIV) genes, and the development of cancer." (PMID 37061003, 2023). "As expected, we found genes dictating the CSC phenotype and behavior, including, but not limited to, cancer stemness (Myc and Sox) and epithelial-to-mesenchymal transition (EMT) (Gata6 and Tfcp2)." (PMID 36002648, 2022). "Factor quinolinone inhibitors are promising anti-cancer compounds, initially characterized as specific inhibitors of the oncogenic transcription factor LSF (TFCP2)." (PMID 34876605, 2021). "In GE2-HCC, top potential transcriptional activators included transcription factors with reported tumour-promoting activity in HCC and/or other cancer types, e.g., NKX6-1, POU2F1/2, cJUN, E2F1, HSF2, SRF, TFCP2 and NFY." (PMID 33541355, 2021). "ALK alterations, namely inversions and intragenic deletions, as well as ALK protein overexpression seen via IHC, commonly co-occur with TFCP2 fusion, and the upregulation of ALK activity leads to increased cell proliferation and migration in multiple cancer types." (PMID 40361368, 2025). "In accordance with FN1 and TJP1 roles in aggressive metastatic cancer cells, the former promotes and the latter suppresses the cancer cell aggression, western blotting demonstrated that FN1 was positively regulated and TJP1 was negatively regulated by TFCP2 in human HCC cells." (PMID 25609232, 2015).
tumor (22 papers, 2014 to 2025). "In this multi-institutional study, due to the rarity of these tumours we hereby report a case series (four cases) of head and neck RMS in adults harbouring TFCP2 mutations along with diagnostic, therapeutic and prognostic details." (PMID 41497928, 2025). "In patient TFCP2-HD-5, CDKN2A deletions were present at both time points, 32 months apart, but additional mutations occurred in the advanced tumor." (PMID 38168093, 2024). "Unexpectedly, the tumor shows TFCP2 rearrangement with coexistence of increased copy numbers of EWSR1 and ROS1 gene and MET gene mutation." (PMID 36998041, 2023). "Together, these results indicate that TFCP2 plays a role in the regulation of HS fine structure and specific HS-protein interactions, the organization of which is important for development and tumor progression." (PMID 37061003, 2023). "The regulation of cholesterol metabolism by TFCP2 that we revealed further highlights the important role of TFCP2 in tumor metabolism." (PMID 34804919, 2021). "Knockdown of TFCP2 significantly inhibited tumor cell growth in HepG2 and BEL-7402 cells compared with the control cells." (PMID 25609232, 2015). "The functions of TFCP2 in tumor metabolism are poorly understood so far." (PMID 34804919, 2021). "TFCP2L1 is a member of the TFCP2/TFCP2L1/UBP1 subfamily of transcription factors that contributes to the maintenance of stemness in pluripotent stem cells and can also exhibit tumor suppressive activity and modulate differentiation." (PMID 37270599, 2023). "The first was a congenital SSRMS tumor in the forearm of a 2-week-old girl with a TEAD1::NCOA2 gene fusion (case 7), and the second was an intraosseous SSRMS in the base of the skull of a 12-year-old boy with a FUS::TFCP2 gene fusion (case 8)." (PMID 40923514, 2025). "TFCP2 functions as a co-factor for YAP-dependent transcription in liver malignancy and pharmacological targeting of this factor in HCC leads to decreased tumor growth in mice." (PMID 37061003, 2023). "Therefore, we employed FISH to determine whether the tumor harbors TFCP2 rearrangement or not." (PMID 36998041, 2023). "In addition, unlike adjacent non-tumour specimens, tumour specimens with higher CCT3 often had higher YAP/TFCP2, and vice versa." (PMID 31501420, 2019).
TFCP2 also shares sentences with these, for which no sentence is quoted: alveolar rhabdomyosarcoma (2 papers); embryonal rhabdomyosarcoma (2); epithelioid sarcoma (2); adamantinoma (1); AIDS (1); alveolar soft part sarcoma (1); angiosarcoma (1); bone sarcoma (1); bone tumors (1); cervical adenocarcinoma (1); chondrosarcoma (1); clear cell sarcoma (1); endometrial cancer (1); epithelioid hemangioendothelioma (1); Ewing sarcoma (1); glial tumor (1); glioblastoma (1); head and neck tumors (1); lung carcinoma (1); mood disorder (1); odontogenic neoplasm (1); oral squamous cell carcinoma (1); osteosarcoma (1); ovarian carcinoma (1); pancreatic adenocarcinoma (1); psoriasis (1); soft tissue sarcoma (1); soft tissue tumors (1); undifferentiated sarcoma (1).